IL1B (interleukin 1 beta)
Diseases named in the same sentence as IL1B in open-access papers (continued):
Sharing a sentence is not in itself a finding about the gene and the disease.
Alzheimer disease (continued). "Further, the administration of vitamin C (200 and 400 mg/kg body weight) can restore colchicine induced memory impairments and also decrease hippocampal TNF-α and IL-1β concentrations in colchicine induced Alzheimer’s disease rats." (PMID 35866081, 2022). "Long-term administration of berberine increases the expression of IL-1β and inducible nitric oxide synthase (iNOS) in Alzheimer’s disease mice hippocampus, and ameliorate memory impairment." (PMID 35668943, 2022). "In a study, rutin showed a reduced production of TNF-α and IL-1β production, which are very common pro-inflammatory factors in the microglia in Alzheimer’s disease." (PMID 36145202, 2022). "In the central nervous system, the significant elevation of IL-1β in the cerebrospinal fluid of brain injury, Alzheimer’s disease, and multiple sclerosis depends on the activation of NLRP3 within microglia." (PMID 35754513, 2022). "Aβ plaques not only induce oxidative stress and damage neurons, but also activate NLRP3 inflammasomes further releasing IL-1β to trigger neuroinflammation in patients with Alzheimer’s disease." (PMID 36009120, 2022). "Bifunctional molecule BPBA inhibits Aβ aggregation and NLRP3 inflammasome activation, thereby decreasing ROS and IL-1β in vitro and vivo; it synergistically prevents Alzheimer's disease via alleviating Aβ neurotoxicity and reducing neuroinflammation." (PMID 35382471, 2022). "For example, high levels of IL-1β are detected in microglial cells surrounding amyloid β (Aβ) plaques in Alzheimer's disease (AD) patient brains." (PMID 36688153, 2022). "Increased levels of TNFα, IL1β, and IL6 in the serum of elderly are associated with the development of several aging-related diseases, including Alzheimer’s disease (AD) and type 2 diabetes." (PMID 39872161, 2022). "β-Asarone protects cognitive function by inhibiting ACh esterase and suppressing tumor necrosis factor-α (TNF-α) and interleukin-1β (IL-1β) secretion among Alzheimer’s disease-induced rats." (PMID 36340563, 2022). "For this purpose, Regnase-1 was overexpressed in primary-culture chondrocytes via Ad-Regnase-1 infection, and the chondrocytes were stimulated with IL-1β." (PMID 33853646, 2021). "Regnase-1 protein levels were also increased by IL-1β treatment or Ad-Regnase-1 infection in primary-culture chondrocytes." (PMID 33853646, 2021). "In SWS and plasma of patients with Alzheimer’s disease, the IL-1β—concentration was significantly higher (↑24% p ≤ 0.0001, ↑59% p = 0.0092) compared to the control group." (PMID 34903846, 2021). "TXNIP up-regulation sustains neurodegeneration by activating NLRP3 inflammasome, and enhancing the expression of caspase-1 and IL-1β in the brains of Alzheimer's disease patients." (PMID 33509083, 2021). "We and others have previously reported that n-3 PUFAs, especially EPA, exerted antineuroinflammatory properties in vivo in animal models of Alzheimer’s disease, Parkinson’s disease, and IL-1β induced neuroinflammation." (PMID 34822458, 2021). "Our data demonstrate that caspase-1/IL-1β represses membrane transport of GluA1 by inhibiting the interaction between Stargazin in Alzheimer's disease." (PMID 33509083, 2021). "NLRC4 inflammasome induces neuroinflammation and contributes to memory impairment in Alzheimer's disease rats through the activation of caspase-1 and IL-1β." (PMID 33509083, 2021). "In conclusion, our data demonstrate that caspase-1/IL-1β participates in pathogenesis of Alzheimer's disease." (PMID 33509083, 2021). "Previous study has reported that caspase-1 and its downstream inflammatory factor IL-1β are closely related to Alzheimer's disease." (PMID 33509083, 2021). "Caspase-1/IL-1β represses membrane transport of GluA1 by inhibiting the interaction between Stargazin in Alzheimer's disease." (PMID 33509083, 2021). "In Alzheimer’s disease cases, IL-15, IL-1β, IL-6, TNF-α, and IL-8 were higher in those with than without infection." (PMID 33723589, 2021).
Alzheimer disease (continued). "A tauopathy mouse model in one study showed that the earliest stages of the characteristic neurodegeneration in Alzheimer’s disease included activation of microglial cells, elevated proinflammatory cytokine levels such as IL-1β, and neuronal damage." (PMID 34209512, 2021). "For example, d-limonene decreased NO levels in Aβ42-expressing fly heads, and linalool reduced the levels of the pro-inflammatory markers p38 MAPK, NOS2, COX2 and IL-1β in the brain of a triple transgenic mouse model of Alzheimer’s disease (3xTg-AD)." (PMID 32235725, 2020). "IL-1α and IL-1β have been identified as potent pro-inflammatory cytokines in many neurodegenerative diseases such as Alzheimer’s disease, Parkinson’s disease or multiple sclerosis, and have been suggested to accelerate the progression of neurodegeneration." (PMID 32933002, 2020). "IL-1β is an immunomodulatory cytokine that is overexpressed in the brains of patients with Alzheimer’s disease (AD)." (PMID 33257576, 2020). "An increase in IL-1β value was observed in patients with neurodegenerative diseases, eg, Alzheimer’s disease." (PMID 31044590, 2019). "Administration of a reversible small caspase-1 specific inhibitor VX-765 in Alzheimer’s disease model of mice showed improvement of mice clinical behaviors, resulted in decrease in hippocampal and cortical IL-1β levels and prevented amyloid beta deposit." (PMID 31892810, 2019). "Previous work from our lab has shown that IL-1β induces significant recruitment of neutrophils, and neutrophils have been shown to modulate Alzheimer’s disease pathology." (PMID 31822279, 2019). "Quercetin treatment of 3xTg Alzheimer's disease mice decreased IL-1β/COX-2/iNOS proinflammatory signaling in the hippocampal CA1 region." (PMID 31565046, 2019). "In other studies, it has been shown a higher serum level of IL-1β in patients with Alzheimer disease who carry −511T/T genotype." (PMID 31001258, 2019). "IL-1β became an important therapeutic target in different inflammatory diseases, immunity disorders, Alzheimer’s disease, and various tumors." (PMID 31684176, 2019). "It has been reported that elevated levels of IL-1β were detected in patients with early-onset Alzheimer’s disease." (PMID 31128596, 2019). "Brain inflammation including increases in inflammatory cytokines such as IL-1β is widely believed to contribute to the pathophysiology of Alzheimer’s disease." (PMID 29712570, 2018). "A dramatic cautionary tale is supplied by a study that investigated the role of IL-1β in Alzheimer’s disease." (PMID 29410649, 2018). "A recent meta-analysis study reported significantly higher levels of the proinflammatory cytokines TNF-α, IL-6, IL-1β, IL-2, and IL-18 in peripheral blood samples of patients with Alzheimer's disease (AD) compared with a control group." (PMID 30510525, 2018). "On the contrary, several studies have reported that activation of MC4R obviously inhibited the overexpression of TNF-α, IL-6, and IL-1β in cerebral ischemia, Alzheimer’s disease, and subarachnoid hemorrhage." (PMID 29642894, 2018). "Inhibition of IL-1β signaling attenuates tau pathology and restores neuronal β-catenin pathway function by reducing NF-κB activity in an Alzheimer’s disease model." (PMID 29571298, 2018). "Elderly with Alzheimer’s disease were significantly higher in their peripheral IL-1β levels than control participants (pooled SMD: 1.37, 95% CI: 0.06–2.68, z = 1.98, p = 0.041)." (PMID 30104698, 2018). "This cell-based litmus gene assay identified six genes (CCL20, CEMIP, IL1B, IL8, PRG2, PTGS2) as potential biomarkers of plasma quality control and the SPC25 gene as a diagnostic biomarker of Alzheimer’s disease (AD)." (PMID 29203810, 2017). "Altered IL-1β signaling has also been demonstrated to occur in common neurodegenerative diseases such as Alzheimer's disease, in which neurogenic changes have also been reported." (PMID 28733362, 2017).
Alzheimer disease (continued). "The clinical study also reported that the levels of TNF-α and IL-1β in blood and cerebrospinal fluid of patients with Alzheimer's disease were significantly higher compared with general population." (PMID 29190943, 2017). "It has been shown in mouse models of prion disease and Alzheimer’s disease (AD) that pre-symptomatic challenge to the CNS markedly increased expression of IL-1β and iNOS during disease progression." (PMID 28839214, 2017). "Mefenamic acid treatment completely abated Alzheimer's disease-related neuroinflammation with levels of microglial activation and IL-1β expression reduced to that of wild-type mice." (PMID 27509875, 2016). "In other studies, increased levels of TNF-α and IL-1β were found in the cerebrospinal fluid and plasma in patients with Alzheimer’s disease." (PMID 26432692, 2016). "This is particularly pertinent at the present time as IL-1β appears to be a key player in the pathogenesis of neurodegenerative diseases such as Alzheimer’s Disease and Parkinson’s Disease [for reviews, see 1, 2]." (PMID 26989349, 2016). "Although IL-1β is quite frequently described in Alzheimer’s disease, whereas only few reports have investigated its levels in MCI." (PMID 26432692, 2016). "The proinflammatory cytokine interleukin-1β (IL-1β) is overexpressed in Alzheimer disease (AD) as a key regulator of neuroinflammation." (PMID 26818951, 2016). "During Alzheimer’s disease (AD), elevation of interleukin 1 beta (IL1β) stimulates the expression and processing of the amyloid precursor protein and accelerates amyloid plaque deposition." (PMID 26465009, 2015). "Clearly, further in vivo investigation into the role of IL-1β-mediated brain iron uptake is required before a link to the progression of Alzheimer’s disease can be made." (PMID 25311416, 2014). "Alzheimer's disease cortex showed significantly increased mRNA and protein levels of IL-1β, TNFα, GFAP, CD11b, cPLA2 IVA sPLA2 IIA COX-1 and COX-2, but decreased levels of pre-synaptic synaptophysin (SYP) and post-synaptic drebrin (DBN1)." (PMID 25329999, 2014). "Wnt5a was upregulated in the Alzheimer’s disease mouse brain due to β-amyloid peptide, inducing neuroinflammation and neurotoxicity via inflammatory cytokines IL-1β and TNF-α." (PMID 24993819, 2014). "Increased microglial expression of IL-1β has been reported in Alzheimer's disease; this chronic expression is thought to contribute to plaque formation and precedes neurodegeneration." (PMID 25124807, 2014). "miR-101 reduced APP expression after prolonged IL-1β treatment, suggesting a role for miR-101 in the control of APP expression in response to IL-1β in Alzheimer's disease." (PMID 22312330, 2012). "Astrocyte activation and overexpression of cytokines and chemokines like IL-1β, TNF-α and CXCL8 have been associated with Alzheimer’s disease." (PMID 23029125, 2012). "Activation of TLR4 is reported to be associated with increased production of TNF-α and IL-1β in the CNS of APPswe/PS1 transgenic mice, a mouse model of Alzheimer’s disease (AD)." (PMID 23234315, 2012). "It has been reported that IL1A (-889T) allele upregulates transcription of the gene and thus increases the level of the gene product in Alzheimer's disease as well as the plasma level of IL1B." (PMID 20565898, 2010). "An increasing IL-1β production was observed in patients with Alzheimer's disease and a possible role for IL-1β in the release of the amyloid precursor protein was proposed." (PMID 18710581, 2008). "Animal models of Alzheimer's disease, such as the APP transgenic line Tg2567 carrying the Swedish mutation, also show enhanced levels for TNF-α, IL-1β, IL-1α, chemoattractant protein-1, COX-2 and complement component 1q." (PMID 18564425, 2008).
Alzheimer disease (continued). "For example, in Alzheimer’s disease (AD), the aberrant accumulation of β-amyloid specifically activates intracellular inflammasomes, contributing to the overproduction of the pro-inflammatory factors IL-1β and TNF-α, which impair synaptic signaling efficiency." (PMID 40430556, 2025). "Research indicates that TNF-α is one of the main neuroinflammatory mediators, responsible for microglial activation, which leads to the release of additional pro-inflammatory cytokines, such as IL-1β, exacerbating neurodegenerative processes in Alzheimer’s disease." (PMID 40137151, 2025). "However, we cannot draw broader conclusions about the role of IL-1β or IL-1R1 signaling in Alzheimer’s disease." (PMID 41191631, 2025). "Furthermore, in vivo administration to Alzheimer’s disease mouse models resulted in better memory, reduced expression of inflammatory compounds (NF-κB, IL-6, IL-1β, and GFAP), and improved synaptic plasticity, mediated by synaptophysin." (PMID 41007636, 2025). "Finally, the most recent prospective cohort study identified elevated IL-1β and reduced IL-10 levels as predictors of Alzheimer’s disease in a clinical population of women with LLD." (PMID 39922907, 2025). "Moreover, CH25H expression was upregulated, and 25-HC promoted IL-1β-mediated neuroinflammation in brain tissue of patients with Alzheimer's disease." (PMID 38716981, 2024). "For example, postmortem analyses have revealed increased levels of IL-1β and IL-6 in the hippocampi of aged humans, supporting the inflammatory hypothesis of early Alzheimer’s disease (AD) pathogenesis." (PMID 39301197, 2024). "Finally, a recent study has reported a correlation between leukocyte telomere shortening and increased plasma levels of IL-1β and IL-18 in patients with mild cognitive impairment and Alzheimer disease." (PMID 38300639, 2024). "Thus, the development of drugs or agents targeted on the knots of the mtDNA‐STING‐NLRP3/IL‐1β axis can inhibit neuroinflammation and alleviate the progression of Alzheimer's disease." (PMID 37528567, 2024). "Blocking IL1β signaling rescues cognition in an Alzheimer’s disease mouse model (3xTg-AD mice)." (PMID 38396950, 2024). "A GO/KEGG analysis predicted that the related gene sets in IL-23/IL-1β-cultured MP CD4+ T cells had enrichment of the terms “Alzheimer’s disease,” “Parkinson’s disease,” and “Huntington’s disease”, which are neurological diseases, and enrichment of “cytokine signaling pathway”." (PMID 37121980, 2023). "Furthermore, in the hippocampus, evodiamine significantly reduces neuroinflammation (TNF-α, IL-1β, and IL-6) and glial cell activation, rendering it a potential treatment for neurodegenerative diseases such as Alzheimer's disease." (PMID 37497547, 2023). "Interestingly, in patients with Alzheimer’s disease, significantly decreased LPS-induced release of IL-6 and IL-1β in PBMC after six months of omega-3 supplementation (2.3 g/day) was reported." (PMID 36674453, 2023). "It is also important that IL-1β can increase the activity of acetylcholinesterase by influencing mRNA expression, which increases the dysfunction of the cholinergic system in the pathogenesis of Alzheimer’s disease." (PMID 37047492, 2023). "The binding of these six components to inflammatory mediators (IL-6, TNF-α, IL-1β) and Alzheimer’s disease-related protein targets was studied by molecular docking technology, and it was found that these six components all have low binding energy and good binding fraction." (PMID 36296486, 2022). "In Alzheimer’s disease, β-amyloid plaques are surrounded by reactive glial cells (microglia and astrocytes) showing elevated expression of proinflammatory factors such as IL-1β, IL-6, TNF-α, and nitric oxide, while anti-inflammatory cytokines (TGF-β1 and IL-10) are at reduced levels." (PMID 36298702, 2022). "It is even reported that increased IL-1β induces cognitive decline in Alzheimer’s disease patients." (PMID 35741412, 2022).
Alzheimer disease (continued). "On a similar note, a single LPS injection was found to induce a trained phenotype of murine microglia; this in turn, promoted the neuropathology in a model of Alzheimer’s disease, increasing both amyloid-β levels and the plaque load, and augmented IL-1β levels after brain ischaemia." (PMID 35154147, 2022). "In addition to these monogenic inflammatory diseases, emerging evidence suggests that IL-1β is also involved in complex neurological disorders, such as Alzheimer’s disease (AD)." (PMID 34066649, 2021). "Caspase-1/IL-1β participates in the development of Alzheimer's disease." (PMID 33509083, 2021). "Microglia-derived sEVs can mediate neuroinflammation by secreting pro-inflammatory mediators such as tumor necrosis factor-α, IL-1β, and miR-155 in traumatic brain injury 44, 45; they are also known to spread the disease by tau propagation in Alzheimer's disease." (PMID 33391532, 2021). "Thus, we used AC-YVAD-CMK to inhibit activity of caspase-1/IL-1β to further explore the mechanism of action of caspase-1/IL-1β in the pathogenesis of Alzheimer's disease." (PMID 33509083, 2021). "This study aimed to explore the mechanism of action of caspase-1/IL-1β in Alzheimer's disease." (PMID 33509083, 2021). "Exercise was able to reduced TNFα and IL-1β levels in transgenic model of Alzheimer Disease." (PMID 32320382, 2020). "In the incidence of Alzheimer’s disease, the release of this inflammatory mediator can cause neuronal cell death, according to a study by Janelsinset al., which stated that the inflammatory mediators TNF-α and IL-1β appears to be directly proportional to Alzheimer’s disease severity." (PMID 34367622, 2020). "Interestingly, APP/PS1 Alzheimer’s disease mice whose astrocytes chronically overexpress IL-1β have reduced hippocampal amyloid load, although contextual and spatial memory impairments in control animals were evident." (PMID 30044427, 2018). "In the neurodegenerative progression of Alzheimer's disease, the deposition and aggregation of amyloid-β can activate a variety of receptors on the surface of microglia, stimulating the releasing of inflammatory cytokines such as IL-1β." (PMID 30105072, 2018). "IL-1β, in conjunction with other inflammatory mediators, has shown to be induced by the activation of microglia cells, which can lead to neuronal death, and thus to the progression of Alzheimer’s disease." (PMID 27294919, 2016). "Additionally, in a transgenic mouse model for Alzheimer's disease, beta-amyloid induced upregulation of IL-1β within the CNS coincided with reduced numbers of ChaT positive neurons and attenuated Ach release." (PMID 24376764, 2013). "However, IL-1β is produced in high levels in many pathological conditions that include ischemic stroke, Alzheimer's disease, Down syndrome, multiple sclerosis, Parkinson's disease, epilepsy, amyotrophic lateral sclerosis and HIV-associated dementia." (PMID 22413888, 2012). "The observed expression of cytokines TNF-α and IL-1β by activated glial cells, is consistent with expression of these cytokines in brains of experimental animal models of Alzheimer's and in the brain of Alzheimer's disease patients." (PMID 16174294, 2005). "The pathological features of these patients overlap with those of Alzheimer’s disease (AD) and Parkinson’s disease (PD) and are presumably caused by direct neural damage and long-term production of proinflammatory cytokines (e.g., IFN-γ, TNFα, Il-1β) secreted by WNV specific T cells." (PMID 34440903, 2021). "Thus, this article aimed to explore whether caspase-1/IL-1β can affect GluA1 membrane transport by regulating the interaction between Stargazin and GluA1 in Alzheimer's disease." (PMID 33509083, 2021). "Thus, our research provides a theoretical basis for the pathogenesis of Alzheimer's disease, and caspase-1/IL-1β may be a target for Alzheimer's disease treatment." (PMID 33509083, 2021).